AR (androgen receptor)
Diseases named in the same sentence as AR in open-access papers (continued):
Sharing a sentence is not in itself a finding about the gene and the disease.
prostate carcinoma (continued). "For example, T cell infiltration of the prostate induced by androgen withdrawal has been found in patients with prostate cancer; the androgen-androgen receptor (AR) system plays vital roles in prostate cancer development and progression." (PMID 27475327, 2016). "On the contrary, miR-644a overexpression was shown to downregulate an isoform of the androgen receptor, and decrease viability in prostate cancer cell lines." (PMID 27409664, 2016). "A log2 ratio-based copy number analysis detected common genomic abnormalities in prostate cancer including AR amplification in 5/10 CRPC patients." (PMID 27127882, 2016). "The androgen receptor (AR) is a pivotal drug target for the treatment of prostate cancer, including its lethal castration-resistant (CRPC) form." (PMID 26813233, 2016). "AR signaling can promote prostate cancer through the upregulation of G6PD and thus providing sugars via the pentose phosphate pathway." (PMID 27609145, 2016). "A reporter assay in human prostate cancer cells that displayed suppressed AR signaling by SGTA showed recovery of AR signaling by REIC/DKK-3 expression." (PMID 26658102, 2016). "In vitro studies demonstrated that dihydrotestosterone (DHT) activated the HIF-1 mediated gene expression, and hypoxia enhanced the AR-induced promoter activity of human PSA gene in prostate cancer cells." (PMID 26919249, 2016). "DIM deterred EMT in prostate cancer cells by blocking AR signaling and the expression of prostate-specific antigen (PSA), an AR-target gene, resulting in the reduction of the expression of EMT markers, ZEB1, N-cadherin and fibronectin." (PMID 27231938, 2016). "Activation of androgen/AR signaling has a positive effect on prostate cancer cell growth in vitro and in vivo." (PMID 27144435, 2016). "HDACis have been shown to downregulate estrogen receptor (ER) and androgen receptor (AR) mRNA in receptor-positive breast and prostate cancer cells." (PMID 27752293, 2016). "The ability of these distinct antioxidants to abrogate the actions of TQ on AR protein in prostate cancer cells is the focus of future studies." (PMID 26986969, 2016). "To continue to elucidate the factors and pathways that participate in AR signaling in prostate cancer, we performed a genome wide RNAi screen to identify new AR regulators that contribute to AR activity and potentially CRPC." (PMID 27363033, 2016). "In contrast, androgen-responsive prostate cancer models expressing exclusively AR(FL), such as LNCaP, offer insights into steroid-dependent gene regulation." (PMID 27623747, 2016). "This was followed by functional analyses of homologous factors in human prostate cancer cells, revealing several new factors that regulate AR activity and prostate cancer cell proliferation." (PMID 27363033, 2016). "In prostate cancer cell lines expressing AR, treatment with androgens led to significant induction of Slug within 2 h of treatment, suggesting a direct up-regulation." (PMID 26797644, 2016). "Here, we expanded these efforts to include analysis of several breast and prostate cancer cells specifically looking for the effects of EDCs on AR levels and/or localization." (PMID 26918604, 2016). "ADT works to reduce prostate cancer cell gene transcription through the reduction of circulating androgens capable of binding to the androgen receptor signaling proliferation." (PMID 26977321, 2016). "DIM inhibits cell growth and induces apoptosis in prostate cancer partially through the regulation of Akt/FOXO3a/GSK-3/β-catenin/AR signaling axis." (PMID 26918831, 2016). "A recent AR ChIP-seq study in prostate cancer revealed AR occupancy at the DNAH8 promoter, suggesting that DNAH8 expression has the potential to be regulated by AR." (PMID 27363033, 2016).
prostate carcinoma (continued). "Combining the AR antagonist bicalutamide with the HDAC inhibitor vorinostat induces synergistic cell death of prostate cancer cells, with multiple features characteristic of apoptosis." (PMID 26907477, 2016). "Inhibition of the AR suppresses cell cycle progression by inhibiting the function and activity of cyclins and CDKs in androgen-dependent prostate cancer cells." (PMID 27399684, 2016). "In the present study, we define a novel functional role for master epithelial plasticity driver, Snail, in AR regulation during prostate cancer progression to treatment resistant disease." (PMID 27409172, 2016). "The androgen receptor (AR) plays a central role in prostate cancer (PCa) development and progression." (PMID 26636645, 2016). "The androgen receptor (AR) plays a key role in prostate cancer carcinogenesis and prostate cancer cells are generally sensitive to the initial androgen blockade treatment." (PMID 26814431, 2016). "In prostate cancer cell lines downregulation of the AR increases STAT3 signaling, which is required for CSC maintenance." (PMID 26880966, 2016). "The androgen receptor (AR) is a ligand-activated transcription factor that is central to the initiation and progression of prostate cancer." (PMID 27120785, 2016). "Expression of BR is negatively regulated by AR signaling in prostate cancer, and our data suggest that this this is likely the case in breast cancer as well." (PMID 27386391, 2016). "Collectively, these findings highlight AR-GSR-driven AR-Vs as important mediators of resistance and attractive therapeutic targets in prostate cancer." (PMID 27897170, 2016). "To model the innate heterogeneity among patients, we cultured four distinct AR-positive prostate cancer cell lines continuously in enzalutamide for at least six months upon which they were considered enzalutamide resistant (EnzR)." (PMID 27036029, 2016). "SIAH2 was reported to increase in castration resistant prostate cancer and stimulate castration resistant activation of AR." (PMID 27058417, 2016). "Androgen signaling is a key driver of prostate cancer growth and as such, factors regulated by the AR are likely to be important in proliferation." (PMID 25693800, 2015). "Inhibition of Src and Lyn with dasatinib decreased prostate cancer growth and lymph node metastasis in AR-independent and -dependent xenograft models." (PMID 25730905, 2015). "The action of paclitaxel and bicalutamide is partly supported by the findings that taxanes are known to inhibit the androgen-independent activation of AR by the action of FOXO1 in prostate cancer." (PMID 25781993, 2015). "We next sought to define the molecular actions of AR in PShTert-AR myofibroblasts, and to contrast those from androgen responses of prostate cancer epithelial C4-2B cells." (PMID 25965833, 2015). "Data in this paper shows that decreasing LMTK2 expression in prostate cancer cells deprived of androgen results in significantly higher levels of FKBP51 protein as well as increased mRNA levels of AR-dependent genes (KLK2, S100P, TMPRS22 and PSA)." (PMID 26008968, 2015). "Second, expression of AR-V transcripts in breast cancer generally tracked with that of AR-FL, a feature observed in prostate cancer cells and tissues." (PMID 26554309, 2015). "In recent studies, Tokai reported that gal suppressed castration-resistant and enzalutamide-resistant prostate cancer growth in vitro and also blocked nuclear translocation and decreased AR dependent genes (PSA, TMPRSS2, and Nkx3.1)." (PMID 26196320, 2015). "Numerous studies have reported that AR stimulated tumour cell migration, such as during prostate cancer cell invasion and oesophageal cancer cell migration." (PMID 26459317, 2015). "Next, we determined if AR negatively regulates celastrol-induced autophagy through inhibition of miR-101 expression in prostate cancer cells." (PMID 26473737, 2015).
prostate carcinoma (continued). "Much has been learned about the pivotal role of the AR in more than 70 years since androgens were first identified as the major drivers of prostate cancer." (PMID 26491675, 2015). "Our report shows that LMTK2 is an essential negative regulator of AR transcriptional activity and knocking down its expression in prostate cancer cells leads to significant increase in the AR activity and also an increase in tumorogenecity and cell viability." (PMID 26008968, 2015). "PlncRNA-1, prostate cancer up-regulated long noncoding RNA 1, has been reported to be up-regulated in prostate cancer and to be involved in reciprocal communication with AR, which contributes to prostate carcinogenesis." (PMID 26110379, 2015). "More importantly, CXCL11 and CXCL12 were able to attenuate the expression of endogenous ARGs, demonstrating crosstalk between chemokine/chemoreceptor pathways and AR-mediated gene expression programs in prostate-cancer cells." (PMID 25884570, 2015). "A relevant example of this modulatory function is the Lysine Specific Demethylase 1A (KDM1A/LSD1) that was recently described as corepressor and coactivator for the androgen receptor (AR) in prostate cancer." (PMID 26117541, 2015). "Retention of androgen receptor (AR) signalling in castrate-resistant prostate cancer (CRPC) highlights the requirement for the development of more effective AR targeting therapies." (PMID 26336819, 2015). "ERG also increases androgen receptor (AR) binding in mouse prostate, and increases AR transcriptional output in PTEN-deficient prostate cancer patients." (PMID 26310325, 2015). "We transfected two known AR-positive prostate cancer cell lines, LNCaP and VCaP, with siRNAs against AR and estimated the CIP2A protein levels." (PMID 25965834, 2015). "This suggested that PABPC1 plays a role in the proliferation of AR-positive prostate cancer cells including castration-resistant C4-2 cells." (PMID 26176602, 2015). "We have dissected androgen action on the G1/S-phase transition of the cell cycle in HPr-1AR human prostate epithelial cells and PC3-Lenti-AR prostate cancer cells." (PMID 26372468, 2015). "Collectively, these findings suggest that stromal AR can play a pro-proliferative, pro-adhesive and/or anti-migratory role in prostate cancer." (PMID 25965833, 2015). "In the AR+ prostate cancer cell line LNCaP, siRNA-mediated knockdown of TRPM8 or using a chemical blocker of TRPM8 (capsazepine) reduced cell viability (by MTT assay) and induced apoptotic nuclei." (PMID 26512697, 2015). "AR reduction by celastrol in prostate cancer xonegraft tissues demonstrates its potential application for prostate cancer treatment." (PMID 26473737, 2015). "The Pten null mouse model of prostate cancer is poorly responsive to androgen ablation therapy including surgical castration and androgen receptor targeted therapy." (PMID 26196517, 2015). "HOXB13 promotes or represses prostate cancer cell proliferation depending on the cellular context, such as with androgen receptor expression." (PMID 25944620, 2015). "Androgen receptor (AR) signaling pathway is very important in prostate cancer, which regulates many other genes involved in tumor progression or tumor suppression." (PMID 25860954, 2015). "FAIRE-seq analyses in prostate cancer specimens led to the identification of a large set of transcription factor motifs, including AR and multiple of its interaction partners." (PMID 26412853, 2015). "The VCaP human prostate cancer cell line expresses wild type AR and contains the TMPRSS2-ERG fusion." (PMID 26571387, 2015). "Due to its ability to directly interact with and be activated by the androgen receptor (AR), PRK1/PKNα has been strongly implicated in androgen-associated prostate cancer and in ovarian serous carcinoma." (PMID 26296974, 2015). "In prostate cancer (PC), 5AZA2 targets multiple genes including the tumor-suppressor miR-146a microRNA and the androgen receptor (AR)." (PMID 25699047, 2015).
prostate carcinoma (continued). "Recently it was demonstrated that there is a bidirectional crosstalk between PI3K and AR survival pathways in PTEN-negative prostate cancers." (PMID 26506516, 2015). "We demonstrate that CIP2A is overexpressed in PC and CRPC cases and promotes the viability and clonogenicity of AR-responsive prostate cancer cells." (PMID 25965834, 2015). "Evidence has revealed that this gene is expressed in prostate cancer, particularly in AR-positive cell lines." (PMID 26110379, 2015). "Current therapies for prostate cancer include antiandrogens, inhibitory ligands of the androgen receptor, which repress androgen-stimulated growth." (PMID 25693800, 2015). "Despite AR in epithelial cells being more related to clinical parameters of histologically aggressive disease, our data suggest the intriguing possibility that AR in fibroblasts plays a more critical role in protecting against prostate cancer progression." (PMID 25965833, 2015). "This study identified PABPC1 as a novel AR co-regulator capable of modulating AR function and subcellular localization in prostate cancer cells." (PMID 26176602, 2015). "The androgen receptor (AR) is a nuclear receptor that has a key role in prostate cancer carcinogenesis and progression, and ARs translocate from the cytoplasm into the nucleus after activation by androgenic hormones." (PMID 26059743, 2015). "siRNA/shRNA based silencing of these lncRNAs in prostate cancer cell lines inhibited cell proliferation and induced apoptosis by decrease in AR expression." (PMID 26082843, 2015). "miR-190a and AR were inversely correlated in human prostate cancer (r = −0.3935, p = 0.012, n = 40), further supporting the results obtained from in situ hybridization." (PMID 26314494, 2015). "Many of these aberrations were specific to the primary tissue of origin of the cancer, for example, lung developmental transcription factor NKX2-1 in lung cancer, AURKA in colon cancer and AR in prostate cancer." (PMID 25889064, 2015). "Western blot analysis was used to evaluate AhR and AR protein expression in androgen-sensitive LNCaP and castration-resistant C4-2 prostate cancer cells in the presence of TCDD and R1881." (PMID 26154658, 2015). "Based on this, we assessed genomewide androgen receptor/chromatin binding and identified a distinct androgen receptor/chromatin binding profile between primary prostate cancers and tumors with an acquired resistance to therapy." (PMID 26412853, 2015). "Our previous experience indicated that although EBR (25 μM) was a strong apoptotic inducer in LNCaP (AR+) prostate cancer cells, it was also surprisingly effective in inducing apoptosis in DU 145 (AR-) cells." (PMID 26353013, 2015). "A more recent study by Prensner and colleagues, however, refutes that PCGEM1 and PRNCR1 interact with the androgen receptor and that either gene is a component of androgen receptor signaling or is involved in castration-resistant prostate cancer." (PMID 25849966, 2015). "A variety of smaller AR isoforms have been previously identified and characterized in prostate cancer cells." (PMID 26317111, 2015). "Recent studies have shown that AR expression level was different in prostate cancer cells, played a different role." (PMID 25943311, 2015). "ACK1 tyrosine kinase not only interacts with AR in prostate cancer, but has also been shown to interact with estrogen receptor (ER) in breast cancer cells." (PMID 26546517, 2015). "Many prostate cancer cells derived from tumor parenchyma express AR, and they are somewhat dependent on AR activation for growth and proliferation." (PMID 26372468, 2015). "The choice of abiraterone as appropriate treatment was based on AR signaling and the model of prostate cancer." (PMID 25699235, 2015). "KDM1A plays important roles in androgen receptor (AR) signaling and is over-expressed in recurrent prostate cancer (PCa)." (PMID 26461474, 2015).
prostate carcinoma (continued). "AR signaling has primarily been studied in prostate cancer, where it plays a central role in both the initiation and progression of disease, but more recent studies have demonstrated the critical role of this pathway in breast cancer." (PMID 26554309, 2015). "In prostate cancer biopsies, immunohistochemistry staining revealed a co-localization of MB with AR and FOXA1." (PMID 26559958, 2015). "Likely as a result of these diverse mechanisms of action, Epi-001 has also been shown to inhibit the growth of AR-null prostate cancer cell lines." (PMID 26566796, 2015). "In terms of potential therapeutic target, small molecules that enhance the activity of LMTK2 can decrease AR-proliferative activity in patients with prostate cancer and more importantly with castrate resistant prostate cancer." (PMID 26008968, 2015). "This analysis yielded functional networks known to be involved in prostate cancer, with one network centered around AR (Fig2H)." (PMID 26412853, 2015). "In fact, it is well known that EGFR/HER2 signaling can constitutively activate AR and render prostate cancer cells refractory to AR blockade." (PMID 25871401, 2015). "Of these drugs, the flavonoid baicalein has been found to promote the apoptosis of prostate cancer cells by regulating AR." (PMID 25957503, 2015). "Given that androgen receptor (AR) signaling is a key driver of the tumor phenotype in both treatment-naïve and castration-resistant prostate cancer, we investigated if AR is able to regulate PBK expression." (PMID 25909225, 2015). "AR plays a critical role in the growth of prostate cancer cells, thus targeting AR signaling pathway is an effective strategy for prostate cancer treatment." (PMID 26473737, 2015). "Two recently approved prostate cancer drugs abiraterone and enzalutamide target the ligand-binding domain of AR by decreasing the ligand availability or inhibiting binding of the ligand." (PMID 25950519, 2015). "For example, KDM4B promotes prostate cancer carcinogenesis via the alteration of AR signaling, and the AR-KDM4A complex promotes prostate cancer progression." (PMID 26397136, 2015). "We tested the ability of the ring-DIMs to kill prostate cancer cells that express a DHT-responsive AR (LNCaP), a constitutively active AR (C42B) and cells lacking AR (DU145)." (PMID 26124925, 2015). "Androgens and the androgen receptor (AR) play crucial roles in male development and the pathogenesis and progression of prostate cancer (PCa)." (PMID 26461474, 2015). "Our study shows that a decrease in LMTK2 expression is associated with human prostate cancer and that LMTK2 and AR are binding partners in prostate epithelial cells." (PMID 26008968, 2015). "VCaP prostate cancer cells have endogenously amplified AR gene and enzalutamide exerted inhibitory effects on proliferation of VCaP cells." (PMID 25705125, 2015). "AR overexpression often leads to enhanced hypersensitivity toward low circulating androgens, which enables prostate cancer cells to further progress despite the use of ADT." (PMID 27340608, 2015). "Our data reveals that TCDD effect on AR expression and activity differs in androgen-sensitive and castration-resistant prostate cancer cell models." (PMID 26154658, 2015). "The discussion of prostate cancer herein is limited as AR and prostate cancer has been reviewed extensively elsewhere." (PMID 25595907, 2015). "Since the vast majority of prostate cancers are AR+, androgen deprivation (suppression) treatment was a rational approach for this malignancy, and has become a cornerstone of treatment for advanced prostate cancer." (PMID 25595907, 2015). "Investigation of the effects of USP26 in prostate cancer is necessary given its role in activity and stability of the androgen receptor and the role of the androgen receptor in prostate cancer." (PMID 25605410, 2015). "Together, these results demonstrate that catalytic Topo II inhibitors can repress AR transcriptional activity in prostate cancer cells." (PMID 26009876, 2015).